ENO1 (enolase 1)
Diseases named in the same sentence as ENO1 in open-access papers (continued):
Sharing a sentence is not in itself a finding about the gene and the disease.
pancreatic cancer (57 papers, 2014 to 2025). "In this study, we used human PDAC samples, PDAC cell lines, and animal models to investigate the mechanism underlying the anti-apoptosis effects induced by ENO1 overexpression in pancreatic cancer cells in a hypoxic microenvironment." (PMID 36476328, 2022). "Intriguingly, a study has reported that the presence of circulating auto-antibodies against ENO1 was associated with better clinical outcomes in patients with advanced pancreatic cancer." (PMID 34136381, 2021). "An increased prevalence of PDA-associated antigen α-enolase (ENO1) has been documented in pancreatic cancer patients (i.e., in 60% cases), which correlated with a better prognosis." (PMID 31652904, 2019). "Among these, ENO1 has been classified as a pancreatic cancer-associated antigen as it is overexpressed in PDAC and induces both humoral and T cell-specific responses in patients." (PMID 25860938, 2015). "Interestingly, high expression of ENO1 was associated with high differentiation of human pancreatic cancer, whereas poorly differentiated pancreatic cancer cells did not express ENO1." (PMID 36476328, 2022). "The current review study identifies 22 IHC biomarkers as diagnostic tools for pancreatic cancer that embrace: Pentraxin-3, ENO1, REG4, POSTN, CA125, CA242, Galectin-1, Galectin-9, Maspin, pVHL, MUC1, MUC5AC, THBS2, LTBP2, CPA4, IMP3, CD13, Dkk1, KOC, S100P, Mesothelin, PAM4." (PMID 34988027, 2021). "This may be associated with the inhibition of pancreatic cancer stem cells by ENO1." (PMID 36476328, 2022). "Here, we found that high expression of enolase-1 (ENO1) is closely related to gemcitabine resistance in pancreatic cancer patients." (PMID 41455715, 2025). "This ENO1-mediated aggregation of RRM2 protein increases the synthesis of dNTPs in pancreatic cancer cells, enhancing the resistance of pancreatic cancer to gemcitabine." (PMID 41455715, 2025). "Regarding ENO, ENO1-specific Tregs accumulate in the tumor tissue of pancreatic cancer, accompanied by decreased levels of ENO1-specific Th17 cells, highlighting a possible role in promoting pancreatic cancer progression." (PMID 41373022, 2025). "In pancreatic cancer, autoantibodies against ENO1 have been shown to reduce tumor growth and metastasis." (PMID 41179678, 2025). "It has been reported that knocking out Eno1 significantly decreases tumor growth in mouse models and that administering anti-ENO1 mAb inhibits the invasiveness of pancreatic cancer cells." (PMID 40892462, 2025). "FAM126A contributes to worse progression of pancreatic cancer by ENO1, a key activator of the PI3K/AKT signaling pathway." (PMID 38891888, 2024). "In genetically engineered mice with pancreatic cancer, ENO1 DNA vaccine elicits antitumor immune responses by decreasing numbers of myeloid-derived suppressor cells and T-regulatory cells and increasing T-helper 1 and 17 responses to prolong survival." (PMID 36845730, 2023). "Herein, we knocked out ENO1 in pancreatic cancer cell lines and evaluated its impact on maintaining the Warburg effect and tumor growth through biochemical and functional approaches." (PMID 36845730, 2023). "ENO1 promotes pancreatic cancer cells migration and metastasis through combining with integrins and uPAR." (PMID 36845730, 2023). "The overexpression of ENO1, one of the key enzymes in the glycolysis process, has been identified in several cancers, however, its role in pancreatic cancer (PC) is yet unclear." (PMID 36845730, 2023). "The median survival of patients with high ENO1 expression in pancreatic carcinoma is as short as 8 months, while the median survival time is more than 30 months with low ENO1 expression." (PMID 37731842, 2023). "A key example of a TAA identified by SERPA is alpha-enolase (ENO1), which is overexpressed, acetylated, or phosphorylated in pancreatic cancer." (PMID 36612133, 2022).
pancreatic cancer (continued). "For example, ENO1 was overexpressed in the plasma of patients with pancreatic cancer, and the increased plasma ENO1 level was correlated with prognosis and disease progression." (PMID 35836227, 2022). "The CoCl2-induced hypoxia model and transcriptomic analysis confirmed that hypoxia increased the expression of ENO1 in pancreatic cancer cells." (PMID 36476328, 2022). "More CA9-positive pancreatic cancers were found in the high ENO1 expression group than the low ENO1 expression group." (PMID 36476328, 2022). "The correlations between ENO1 expression and the pathological and clinical features of 84 pancreatic cancer cases were tested with Pearson correlation coefficient analysis." (PMID 36476328, 2022). "Approximately 64.7% of patients with pancreatic cancer with high ENO1 levels showed high-to-moderate differentiation, and 50% of patients with low ENO1 levels showed high-to-moderate differentiation (χ2 = 3.552, P = 0.042)." (PMID 36476328, 2022). "ENO1 regulates pancreatic cancer adhesion, invasion, and metastasis by controlling the expression of α-V/β-3 integrin." (PMID 36620599, 2022). "ENO1 was expressed mainly in the cytoplasm and nuclei of pancreatic cancer cells, whereas CA9 was expressed in the cell membrane." (PMID 36476328, 2022). "Recent studies have found that ENO1 is highly expressed in lung adenocarcinoma, bladder cancer, pancreatic cancer, gastric cancer, colorectal cancer, and other types of tumor tissues." (PMID 35925486, 2022). "ENO1 is expressed in human pancreatic cancer cell lines, pancreatic cancer samples, and pancreatic cancer." (PMID 36476328, 2022). "The prognosis of pancreatic cancer in the high ENO1 expression group was poorer than that in the low expression group." (PMID 36476328, 2022). "Recently, Chinese scholars reported the production of superparamagnetic iron oxide nanoparticles targeting the highly expressed ENO1 in pancreatic cancer tissues." (PMID 35925486, 2022). "More pancreatic cancers with larger tumor diameters were observed in the high ENO1 expression group than in the low ENO1 expression group (χ2 = 5.739, P = 0.043)." (PMID 36476328, 2022). "In this study, 34 pancreatic cancers expressed ENO1 at high levels, and 50 expressed ENO1 at low levels." (PMID 36476328, 2022). "We found that the prognosis of patients with high ENO1 expression was poor, and ENO1 expression was positively correlated with hypoxia, nerve invasion, and vascular invasion in 84 human pancreatic cancer samples." (PMID 36476328, 2022). "To evaluate the expression of ENO1 in the pancreatic cancer cell lines used in this study, we performed Western blot and found that the expression of ENO1 was high in the 5 human PDAC cell lines." (PMID 36476328, 2022). "We detected the activation of ERKs upon CoCl2-induced hypoxia and found decreased ERK activity after ENO1 silencing in pancreatic cancer cells, in agreement with previous findings." (PMID 36476328, 2022). "For example, in pancreatic cancer, silencing ENO1 inhibited the migration and invasion of pancreatic ductal adenocarcinoma cells in vitro and in vivo." (PMID 35251177, 2022). "Approximately 17.6% of patients with pancreatic cancer with high ENO1 levels were younger than 50 years of age, and 6.0% of patients with low ENO1 levels were younger than 50 years of age (χ2 = 2.807, P = 0.092)." (PMID 36476328, 2022). "Consistently, function-inhibitory anti-ENO1 antibodies have been shown to inhibit tumor metastasis in animal models of lung and pancreatic cancers." (PMID 34136381, 2021). "ENO1 has been found to induce autoantibody production in patients with cholangiocarcinoma, breast tumor, head and neck tumor, leukemia, lung tumor, pancreatic tumor, and melanoma." (PMID 33643901, 2020). "ENO1 also regulates pancreatic cancer adhesion, invasion, and metastasis by controlling the expression of αvβ3 integrin." (PMID 32197468, 2020).
pancreatic cancer (continued). "Expression level and location of ENO1 protein in pancreatic cancer cell lines of CFPAC‐1 and MiaPaCa‐2 were detected by Western blotting, flow cytometry and confocal microscopy." (PMID 32285549, 2020). "A previous study reported that ENO1 controls alpha v/beta 3 integrin expression and regulates pancreatic cancer adhesion, invasion, and metastasis." (PMID 33184263, 2020). "ENO1 DNA vaccination has been shown to elicit robust anti-tumor immune response as well as increased survival of pancreatic cancer-bearing GEMM mice." (PMID 31652904, 2019). "A recent study determined the effects of ENO1 on MDSCs functions and effector T-cell responses in a syngeneic transplantable pancreatic cancer model." (PMID 31652904, 2019). "Combined use of AFM and CLSM revealed that ENO1 gene silencing made pancreatic cancer cells coarser, damaging the adhesion between cancer cells, and between cancer cells and stroma, resulting in the invasion and metastasis of pancreatic cancer cells." (PMID 30538002, 2018). "In our previous report, we demonstrated that ENO1 cell surface expression is important for plasminogen-dependent invasion, and that targeting of ENO1 with a monoclonal antibody inhibits the invasiveness of pancreatic cancer cells." (PMID 28086938, 2017). "ENO1 was silenced in a human pancreatic cancer cell line, namely CFPAC-1, through a short hairpin RNA targeting ENO1 3â€2UTR (shENO1)." (PMID 26734996, 2016). "In pancreatic cancer, T cells activated by ENO1-pulsed dendritic cells can lyse pancreatic ductal adenocarcinoma (PDAC) cells in vitro and inhibit the growth of transplanted tumor cells in mice." (PMID 26551021, 2015). "Upregulated expression of ENO1 has been detected in several cancers, such as glioblastoma, head and neck cancer, pancreatic cancer, and prostate cancer." (PMID 25887760, 2015). "Phosphorylated epitope from cell division cycle 25B (CDC25B) was overexpressed in pancreatic cancer (targeting ENO1), while citrullinated epitopes from ENO1 and metallopeptidase 21 (MMP21) were specifically upregulated in ovarian cancer and melanoma, respectively." (PMID 40629481, 2025). "Likewise, ENO1 is expressed in pancreatic cancer and liver cancer cells and ENO1 promotes cell proliferation, migration, invasion, and tumorigenesis in non-small cell lung cancer." (PMID 38675491, 2024). "Altogether, these results suggested that ENO1 may promote the occurrence of various cancers including pancreatic cancer." (PMID 36845730, 2023). "ENO1 may function as a promising and clinically-relevant molecular target for immunotherapeutic strategy, particularly in pancreatic cancer." (PMID 36845730, 2023). "Moreover, the detection of caspase-3 activity and the percentage of apoptotic cells (Annexin V-PI assays) in the shENO1 group supported the anti-apoptotic role of ENO1 in pancreatic cancer cells under normoxia and hypoxia." (PMID 36476328, 2022). "To assess the effects of ENO1 silencing and CoCl2-induced hypoxia on pancreatic cancer transcriptomes, we extracted total RNA from SW1990-shENO1 and SW1990-shNTC cells treated with either CoCl2 or distilled water for 24 h, then performed RNA sequencing analysis." (PMID 36476328, 2022). "To investigate whether ENO1 might be involved in the growth of pancreatic cancer in a hypoxic microenvironment, we established a nude mouse hindlimb model to simulate the hypoxic microenvironment in vivo." (PMID 36476328, 2022). "ENO1 expression in human pancreatic cancer cells was detected with immunohistochemical staining." (PMID 36476328, 2022). "The expression levels of ENO1 in human pancreatic cancer are closely associated with those of the hypoxia marker CA9 as well as nerve and vascular invasion, thus suggesting that ENO1 promotes the invasion and metastasis of pancreatic cancer, in agreement with the results of many in vitro studies." (PMID 36476328, 2022).
pancreatic cancer (continued). "To investigate whether ENO1 has an anti-apoptotic role in pancreatic cancer, we performed Western blot to examine changes in the expression of full-length and cleaved caspase-3 after ENO1 knockdown." (PMID 36476328, 2022). "ENO1 can be used as a therapeutic target for inhibiting the proliferation, migration, and invasion of pancreatic cancer cells, and for improving the survival of patients with pancreatic cancer." (PMID 36476328, 2022). "Multiple lines of evidence reveal that ENO1 is also present on the plasma membrane of cancer cells in non-small cell lung, breast, and pancreatic cancers, where it activates the plasminogen activator receptor (uPAR)/plasminogen/MMP axis, resulting in collagen degradation and cell invasion." (PMID 34136381, 2021). "ENO1 also regulated apoptosis and cell cycle in bladder and pancreatic cancer cells." (PMID 33643901, 2020). "IHC staining demonstrated ENO1 expression in pancreatic tumour tissues of xenograft model." (PMID 32285549, 2020). "In addition, ENO1 is also involved in the development of other cancers, including retinoblastoma, glioma, pancreatic cancer and lung adenocarcinomas." (PMID 31431517, 2019). "The multifunctional glycolytic enzyme α-enolase (ENO1) has been shown to be commonly over-expressed in tumors, and is thus a promising and clinically-relevant molecular target for immunotherapeutic approaches, particularly in pancreatic cancer." (PMID 26734996, 2016). "Further, ENO1 knockdown can sensitize hypoxia-induced chemical resistance in pancreatic cancer cells by regulating REDOX homeostasis, which may be associated with an increase in intracellular reactive oxygen species levels, affecting cell cycle and proliferation." (PMID 36620599, 2022). "Our study reveals a role of ENO1 in pancreatic cancer via RRM2-STUB1 axis and provides a scientific basis for the development of new therapeutic strategies targeting ENO1." (PMID 41455715, 2025). "These vaccines have been studied in relation to a range of targets of pancreatic cancer, such as MUC1, surviving, enolase 1 (ENO1), VEGFR-2, and fibroblast activation protein α-expressing cancer-associated fibroblasts (FAPα+ CAFs)." (PMID 39329989, 2024). "Some studies have suggested that ENO1 can directly activate the PI3K/AKT signaling pathway to promote the proliferation of cancer cells 50, including pancreatic cancer and gastric cancer cells." (PMID 37497003, 2023). "Enolase 1 (ENO1), MUC1, survivin, and VEGFR-2-targeting DNA vaccines are examples of the DNA-based pancreatic cancer vaccines explored so far." (PMID 36224645, 2022). "Abnormally higher circulating ENO1 levels were reported in non-small-cell lung cancer (NSCLC) 38 and pancreatic cancer patients." (PMID 33628097, 2021). "ALDOA and PAF1 have recently been described as oncogenes in PDAC, whereas ENO1, RALGDS, TRIP10, and FLNA are known to mediate pancreatic cancer cell proliferation, survival and migration." (PMID 32029502, 2020). "Recently, the glycolytic enzyme ENO1 has attracted the attention of oncologists because it is dys-regulated in various cancer types, including gastric cancer, HCC, glioma and pancreatic cancer." (PMID 31431517, 2019). "In pancreatic cancer patients, FoxP3+IL-10+TGF-β+ TI Tregs comprised 12% of the ENO1-specific CD4+ T cell population and specifically inhibited the proliferation of autologous ENO1-specific Teff." (PMID 27509527, 2016). "ENO1 was identified as a TAA in lung and pancreatic cancers, and can be detected on the surface of breast, lung, and pancreatic cancer cells." (PMID 26551021, 2015). "Cellular experiments and in vivo experiments confirmed that ENO1 increases the resistance of pancreatic cancer to gemcitabine without relying on its glycolytic enzyme activity." (PMID 41455715, 2025). "Linc-UROD can prevent ENO1 and PKM from being degraded by proteasome by reducing the ubiquitination of ENO1 and PKM proteins, and finally enhance the glycolysis and invasion ability of pancreatic cancer." (PMID 37582735, 2023).
pancreatic cancer (continued). "Additional hyperlipidemia promoted pancreatic carcinoma metastasis in the lung in mice injected through the tail vein, which confirmed that hyperlipidemia accelerated the process of EMT by increasing the expression of ENO1, ENO2, and ENO3, therefore promoting the pancreatic cancer cell metastasis." (PMID 37731842, 2023). "Targeting ENO1 and its downstream ERK phosphorylation therefore may be a promising approach for countering the therapeutic resistance developed during pancreatic cancer growth." (PMID 36476328, 2022). "Immunization with citrullinated Vim and ENO1 peptides increase survival of HLA-DR4 transgenic mice implanted with B16F1 tumors expressing HLA-DR4, as well as Lewis lung carcinoma cells (LLC/2), ovarian cancer cells (ID8), and pancreatic cancer cells (Pan02)." (PMID 36612133, 2022). "Interestingly, GLS inhibition significantly decreased CFPAC-1 survival suggesting that pancreatic cancer cells, known to have specific addiction to glutamine, are markedly more sensitive to GLS inhibition when ENO1 function is impaired." (PMID 26734996, 2016). "GLS inhibition significantly decreased CFPAC-1, but not MDA-MB-231 or NCI-H441 cell survival, suggesting that pancreatic cancer cells are considerably more sensitive to GLS inhibition when ENO1 function is impaired." (PMID 26734996, 2016).